EXT1 (exostosin glycosyltransferase 1)
Diseases named in the same sentence as EXT1 in open-access papers (continued):
Sharing a sentence is not in itself a finding about the gene and the disease.
Multiple osteochondromas (27 papers, 2011 to 2025). Multiple osteochondromas (MO) is characterised by development of two or more cartilage capped bony outgrowths (osteochondromas) of the long bones. "Six patients had pathogenic variants in the EXT1 gene (OMIM: *608177) causing hereditary multiple osteochondromas (OMIM: #608177)." (PMID 40130161, 2025). "An initial diagnosis was made via targeted EXT1 sequencing, which identified a de novo pathogenic variant, confirming a diagnosis of hereditary multiple osteochondromas, or EXT1‐CDG." (PMID 38240170, 2024). "According to the statistics of all mutations on EXT1 in the Multiple Osteochondroma Mutation Database, all variant types were nearly equally distributed on the 11 exons." (PMID 25421355, 2015). "We reported a case of hereditary multiple osteochondromas with a pathogenic EXT1 gene variant." (PMID 41282553, 2025). "Multiple osteochondromas (also called hereditary multiple exostoses) is an autosomal dominant disorder characterized by multiple cartilaginous tumors, which are caused by mutations in the genes for exostosin-1 (EXT1) and exostosin-2 (EXT2)." (PMID 26839764, 2016). "Hereditary Multiple Exostoses (HME), also known as Multiple Osteochondromas (MO) is a rare genetic disorder characterized by multiple benign cartilaginous bone tumors, which are caused by mutations in the genes for exostosin glycosyltransferase 1 (EXT1) and exostosin glycosyltransferase 2 (EXT2)." (PMID 33632255, 2021). "Mutations in members of the EXT gene family, EXT1 or EXT2, have been associated with hereditary multiple osteochondromas." (PMID 39927690, 2025). "Heterozygous loss-of-function variants in the EXT1 and EXT2 genes are the primary cause of hereditary multiple osteochondromas and are identified in the majority of reported cases." (PMID 41282553, 2025). "A large number of studies have found that mutations in EXT1 and EXT2 lead to loss of the protein domain, which is closely related to multiple osteochondromas." (PMID 35899200, 2022). "Multiple osteochondromas (MO; OMIM #133700, #133701), is a rare condition caused by mutations on the exostosin-1 (EXT1) or exostosin-2 (EXT2) gene in 90% of patients." (PMID 33917765, 2021). "Clinical data and mutations identified in EXT1 and EXT2 in 6 Chinese probands with hereditary multiple exostoses." (PMID 31096510, 2019). "Multiple osteochondromas (MO), previously known as hereditary multiple exostosis (HME), is a genetic dominant syndrome occurring at the frequency of 1∶50,000 that is caused by mutation of one of the two EXOSTOSIN (EXT) genes, EXT1 or EXT2." (PMID 22253766, 2012). "Multiple osteochondromas (MO, OMIM 133700) are characterized by a large spectrum of germline mutations scattered along EXT1/EXT2 genes, by the presence of a significant percentage of patients without alterations in the EXT genes and a large phenotypic intra- and interfamilial variability." (PMID 22072915, 2011). "Patients may develop solitary osteochondromas due to injuries at the metaphysis or multiple osteochondromas associated with mutations in the Exostosin 1 (EXT1) and 2 (EXT2) genes, a condition known as hereditary multiple osteochondromas (HMO; previously called hereditary multiple exostoses, HME)." (PMID 39062860, 2024). "There are no data about EXT1 and EXT2 pathogenic variants in patients with multiple osteochondromas in Brazilian population." (PMID 29529714, 2018).
hereditary multiple exostoses (24 papers, 2010 to 2025). An exostosis that has_material_basis_in a mutation on the genes EXT1, EXT2 and EXT3 which results_in multiple bony spurs throughout a child's growth. "Diseases associated with EXT1 include hereditary multiple exostoses, non-small-cell lung carcinoma and chondrosarcoma." (PMID 35850644, 2022). "Hereditary multiple exostoses is an autosomal dominant disorder, caused by pathogenic variants in EXT1 or EXT2 in 70–95% of cases, with EXT1 affected twice as frequently as EXT2." (PMID 31577830, 2019). "Hereditary Multiple Exostoses (HME) is a rare pediatric disorder caused by loss-of-function mutations in the genes encoding the heparan sulfate (HS)-synthesizing enzymes EXT1 or EXT2." (PMID 28445472, 2017). "Here we describe a familial case of osteopoikilosis in which a novel heterozygous LEMD3 mutation coincides with a novel mutation in EXT1, a gene involved in aetiology of multiple exostosis syndrome." (PMID 20618940, 2010). "Notably, deleterious mutations in EXT1 cause the rare disorder Hereditary Multiple Exostoses, which is characterized by the development of benign bone tumors during childhood, a part of which spontaneously regress after adolescence." (PMID 35798875, 2022). "However, although mutations in either EXT1 or EXT2 can result in development of Hereditary Multiple Exostoses, mutations in EXT1 are associated with a higher disease burden." (PMID 25541963, 2014). "We hypothesized that loss of function of EXT1 or EXT2 in subjects with hereditary multiple exostoses (HME) affects pancreatic insulin secretion capacity and development." (PMID 25541963, 2014). "The genetic bone disorder, hereditary multiple exostoses (HME), is caused by mutations in EXT1 and is characterized by multiple benign bony outgrowths." (PMID 34890641, 2022). "Increased cartilage matrix formation also occurs in affected tissue of mouse mutants mimicking Hereditary Multiple Exostoses (HME), a disease linked to aberrant Ext1-expression." (PMID 33918436, 2021). "EXT1 and EXT2 are tumor suppressors, associated with hereditary multiple exostoses, characterized by the development of benign skeletal tumors in patients." (PMID 26482785, 2015). "EXT1 or EXT2 loss of function mutations results in the autosomal dominant disease multiple osteochondromas (MO, OMIM No. 133700 and 133,701), previously also known as hereditary multiple exostoses (HME) and multiple hereditary multiple exostoses (MHE)." (PMID 35103870, 2022).
chondrosarcoma (15 papers, 2011 to 2025). A malignant cartilaginous matrix-producing mesenchymal neoplasm arising from the bone and soft tissue. "The heterozygous loss and homozygous deletion of exostosin 1/2 (EXT1/EXT2) genes have been reported in peripheral chondrosarcomas." (PMID 38275833, 2024). "Overall, mutations in IDH1/IDH2 or EXT1/EXT2 have been shown to have a role in the pathogenesis of most common central or peripheral chondrosarcomas, respectively." (PMID 32295254, 2020). "Moreover, it has been suggested that EXT1 mutations can be associated with a higher risk for chondrosarcoma; if confirmed, this could allow for different screening protocols if the involved gene is known." (PMID 39336760, 2024). "These mutations are early events, and similar alterations are found in chondrosarcomas with the presence of IDH1/2 mutations in central CS and EXT1/2 mutations in peripheral CS." (PMID 36674874, 2023). "Mutations in exostosin glycosyltransferase 1/2 (EXT1/2) genes, which participate in the differentiation of chondrocytes, have been observed in peripheral chondrosarcomas." (PMID 35163019, 2022). "In chondrosarcoma tissues, the expression of EXT1 and EXT2 usually has a significant reduction, whereas SOX9 has a higher expression." (PMID 35760773, 2022). "A minor but not negligible result arising from the present study was the absence even of traces of the linkage region sequence in two CS samples: a chondrosarcoma with EXT1 deletion and the corresponding perichondrium." (PMID 30544937, 2018). "Rarely, persons with multiple hereditary exostoses (EXT1, MIM 608177; EXT2, MIM 608210)—both genes encode glycosyltransferases involved in heparan sulfate production—may also develop chondrosarcomas later in life." (PMID 39941818, 2025). "Genetically, two main groups of chondrosarcomas exist: central chondrosarcomas, characterized by mutations in the isocitrate dehydrogenase genes IDH1 and IDH2, and secondary peripheral chondrosarcomas, characterized by alterations in the exostosin glycosyltransferase 1 (EXT1) and 2 (EXT2) genes." (PMID 32295254, 2020). "Nevertheless, the loss of heterozygosity in the EXT1 and EXT2 genes has been implicated to cause hereditary multiple exostoses, one of the most common inherited musculoskeletal conditions, with an incidence of 1 in 50,000, whose most serious complication is chondrosarcoma transformation." (PMID 32295254, 2020). "Previous findings suggested that EXT1, EXT2, and Sox9 can be considered genetic markers in the diagnosis and prognosis of chondrosarcoma." (PMID 35760773, 2022).
membranous nephropathy (15 papers, 2021 to 2026). "In this context, the exostosin 1 (EXT1)/exostosin 2 (EXT2) heterodimer has emerged as a novel antigen in membranous nephropathy associated with SLE." (PMID 42279461, 2026). "PLA2R, THSD7A, and NELL-1 are causative for primary membranous nephropathy, while EXT1 and 2 are associated with autoimmune disease and secondary membranous nephropathy." (PMID 37477245, 2023). "She had EXT1-associated membranous nephropathy with nephrotic syndrome, high ANA titers, positive dsDNA, and decreased serum complements." (PMID 33655949, 2021). "Alternatively, the antigens EXT 1 or 2 may be involved in our case, as these antigens are associated with autoimmune induced secondary membranous nephropathy." (PMID 37477245, 2023). "A subset of potential antigens, including exostosin 1 (EXT1) and EXT2, as well as neural cell adhesion molecule 1 (NCAM1), has been identified as candidates in secondary membranous nephropathy associated with autoimmune diseases, including MLN." (PMID 41440943, 2025). "Both EXT1/EXT2 and NCAM1 are associated with subepithelial immune deposits, suggesting mechanisms of injury in MLN that are different from other forms of membranous nephropathy." (PMID 41440943, 2025). "Recent developments in mass spectrometry (MS) have revealed target antigens for membranous nephropathy (MN), including phospholipase A2 receptor and exostosin 1/exostosin 2 (EXT1/2)." (PMID 37488532, 2023). "Such important biomarkers include anti-PLA2R and anti-THSD7A antibodies, which are specific to the primary form, as well as exostosin (EXT-1 and EXT-2), as markers of membranous nephropathy secondary to autoimmune diseases, particularly LN." (PMID 39682589, 2024). "A renal biopsy revealed EXT1-positive, PLA2R/THSD7A-negative, membranous nephropathy with IgG and C3 deposition." (PMID 33655949, 2021). "Recently, glomerular subepithelial deposits containing exostosin 1 and exostosin 2 (EXT1/2) were identified in patients with PLA2R-negative and THSD7A-negative membranous nephropathy." (PMID 33916456, 2021). "Not all patients were tested for THSD7A-, NELL1-, or EXT1/2-related antibodies; otherwise, this would have affected the generalizability of the results (other antibody-related membranous nephropathy)." (PMID 41041325, 2025). "As a recently discovered hotspot, EXT1 has been confirmed to be widely expressed in various membranous nephropathies, including lupus membranous nephropathy (LMN), primary membranous nephropathy (PMN), and PLA2R-negative membranous nephropathy and indicates a favorable prognosis." (PMID 40825025, 2025).
breast carcinoma (13 papers, 2017 to 2023). "In breast cancer, EXT1 gene expression was shown to predict a risk of metastasis, and knocking down of EXT1 reduced the colony formation of breast cancer, and effect the therapy resistance." (PMID 33565239, 2021). "Furthermore, EXT1 was shown to induce stemness in MCF-7 breast cancer cells associated with increased epithelial–mesenchymal transition and doxorubicin resistance, which could be antagonized by EXT1 downregulation." (PMID 36982528, 2023). "The genes included NDRG1, PVT1, and EXT1, which are co-located in cytoband 8q24, which is frequently amplified in breast cancer." (PMID 32612361, 2020). "As our research has illustrated that doxo treatment can enrich CSCs with increased EXT1 protein within breast cancer cells, it is possible that tumors grow more aggressively with increased translation of EXT1 protein upon exposure to doxo." (PMID 29050299, 2017). "EXT1 has been evaluated as a potential target in breast cancer and multiple myeloma." (PMID 35710421, 2022). "However, the analysis revealed 3 somatic mutated genes: CDC42BPA, EXT1, and PRC1 significantly associated with both types of breast cancer." (PMID 32724790, 2020). "Hence, these findings may provide a new insight into EXT1 as a promising novel therapeutic target for overcoming breast cancer stemness and chemoresistance in breast cancer patients with anthracycline-based therapeutic resistance." (PMID 29050299, 2017). "EXT1 promotes epithelial–mesenchymal transition (EMT) and migratory behavior in breast cancer cells." (PMID 31847905, 2019). "In this study, we report that CSC-like features are increased in response to hyperactivation of EXT1 in MCF7/ADR, a doxo-resistant breast cancer cell line, than in MCF7, a parental cell line." (PMID 29050299, 2017). "Overall, our results illustrate the novel role of EXT1 as an EMT promoter, eventually resulting in a CSC-enriched phenotype in the doxo refractory breast cancer cell line, MCF7/ADR." (PMID 29050299, 2017). "EXT1 catalyzes the elongation of the HS chain and its inhibition selectively reduced the CSC subpopulation, concomitant with decreased EMT and drug resistance in breast cancer cells." (PMID 37308486, 2023). "Here, we endeavored to investigate the role of EXT1 in cancer cell stemness using the doxo-resistant human breast cancer cell line, MCF7/ADR, established by exposing MCF7, a doxo-sensitive human breast cancer cell line, to serially escalated doses of doxo up to 1 μM." (PMID 29050299, 2017). "Kaplan–Meier analysis showed that the overall survival rates were significantly lower in breast cancer patients with than without amplification of one of these genes (log rank test; NDRG1, P = 0.0554; UBR5, P = 0.0122; MYC, P = 0.0094; EXT1, P = 0.0103; NBN, P = 0.0030; and COX6C, P = 0.0073)." (PMID 28977883, 2017).
autoimmune disease (12 papers, 2021 to 2025). A disorder resulting from loss of function or tissue destruction of an organ or multiple organs, arising from humoral or cellular immune responses of the individual to their own tissue constituents. "EXT1/2 were identified as novel antigens in MN associated with autoimmune disease, particularly lupus nephritis (LN), in which it was found in 32.6% of LN Class V patients." (PMID 40500560, 2025). "In our study, 60% of the samples (3 of 5 cases) from patients with lupus class V showed positive staining of Ext1/Ext2, supporting that they are associated with autoimmune diseases." (PMID 35194125, 2022). "MN podocyte antigens exostosin 1/eoxstosin 2 (EXT1/EXT2), neural cell adhesion molecule 1 (NCAM1), and transforming growth factor-β receptor 3 (TGFBR3) are associated with other autoimmune diseases, especially systematic lupus erythematosus (SLE)." (PMID 36405681, 2022). "Most patients (85%) with EXT1/EXT2-positive MN had other autoimmune diseases including lupus (8/26), revealing EXT1 and EXT2 as potential target antigens for SMN." (PMID 33808418, 2021). "For example, nephrologists appear to adopt a more aggressive malignancy workup for the antigens associated with malignancy, NELL1 and THSD7A, but not for EXT1/2 which has been associated with autoimmune diseases." (PMID 40500560, 2025). "Notably, MN associated with EXT1/EXT2 and NELL1-related malignant tumors may be linked to autoimmune diseases, such as systemic lupus erythematosus and mixed connective tissue disease." (PMID 40852718, 2025). "Exostosin 1 and 2 (EXT1/2) are recently reported antigens of autoimmune disease-related secondary MN." (PMID 37488532, 2023). "As SLE is an autoimmune disorder of the connective tissue, the other top GSEA term is ‘chondrocyte development’, represented by the genes CHST11, COL11A, EXT1, and TGFBR2." (PMID 37048133, 2023). "EXT1 and EXT2 are the primary antigens for a subset of autoimmune diseases, including lupus." (PMID 37048133, 2023).
autism (9 papers, 2008 to 2026). Persistent deficits in social interaction and communication and interaction as well as a markedly restricted repertoire of activity and interest as well as repetitive patterns of behavior. "Genetic analysis on patients affected by hereditary multiple exostosis and autism-associated mental retardation has identified deletion mutations in the gene encoding EXT1." (PMID 29434536, 2018). "Mental impairment and autism have similarly been described in patients with deletion mutations in EXT1, demonstrating a role for HS in synaptic and cognitive function." (PMID 26487777, 2015). "EXT1 was involved in the biosynthesis of heparan sulfate, which played an important role in the development of the nervous systems in the brain, and its deletion caused autism-like behavior in mice." (PMID 33126421, 2020). "In mammals, the elimination of Ext1, a gene encoding an enzyme essential for HS synthesis, causes the attenuation of excitatory synaptic transmission in amygdala pyramidal neurons and results in autism-like behavioral deficits." (PMID 29559501, 2018). "In this context, it is of note that HS deficiency caused by EXT1 or HS3ST5, which encodes an HS synthetic enzyme or an HS sulfotransferase, respectively, are associated with autism." (PMID 34073798, 2021). "Several candidate autism susceptibility genes were hypermethylated (P <0.05) in the HMFA, including Shank3, Cacana1g, Gtf2i, Rapgef4, and Nbea in male offspring and Ext1, Ube3a, Erbb4, Grip1, Grm8, Reeln, Shank3, and Rbfox1 in female offspring." (PMID 24484737, 2014). "An apparent deletion of a single probe in EXT1 gene was observed in an affected boy, in one of his brothers with autism, and in two of three unaffected siblings." (PMID 18925931, 2008). "Late postnatal deletion of Ext1 in a subset of neurons leads to deficits in synaptic function and autism-like social, communication, and stereotypy behaviors in mice through unknown mechanisms." (PMID 30100184, 2018). "Postnatal loss of EXT1 did not cause any brain morphological defects, but resulted in autism-like behavioral phenotypes." (PMID 29434536, 2018). "In addition, postnatal inactivation of Ext1 in mice leads to an autism-like phenotype." (PMID 34073798, 2021). "HS is enriched in synapses of adult neurons, and cKO mice lacking Ext1 in post-mitotic neurons exhibit altered glutamatergic synaptic transmission and develop numerous autism-like behavioral deficits." (PMID 26487777, 2015). "In conditional Ext1 KO mice, in which HS is not synthesized in the excitatory neurons in the forebrain, autism-like deficits were observed as a result of attenuation of EPSCs in the amygdala, presumably owing to the reduction in the number of postsynaptic AMPA receptors." (PMID 41381361, 2026).
lupus (9 papers, 2021 to 2025). "Our patient was diagnosed with EXT1-associated membranous LN according to the Lupus International Collaborating Clinics classification criteria for systemic lupus erythematosus." (PMID 33655949, 2021). "Some of these antigens have shown associations with membranousnephropathy with some features, such as, for example, Sema3B predominating inchildren, THSD7A in some neoplasms, EXT1/2 with systemic lupus erythematosus andother systemic autoimmune diseases." (PMID 37527529, 2023). "Because of the specificity of these biomarkers for lupus, EXT1/EXT2 staining prompts to anticipate later development of lupus disease in young female patients with a diagnosis of “primary” MN." (PMID 33562791, 2021).